BDNF (brain derived neurotrophic factor)
Diseases named in the same sentence as BDNF in open-access papers (continued):
Sharing a sentence is not in itself a finding about the gene and the disease.
depression (continued). "Studies have also examined whether the loss of BDNF signalling, by impairing the function of the TrkB receptor, influences depression-like behaviour." (PMID 22654714, 2011). "Groves critically reviewing all the clinical and preclinical studies regarding the BDNF hypothesis of depression stated that a loss of BDNF is directly involved in the pathophysiology of depression." (PMID 21441870, 2011). "Taken together, CART and its association factors such as BDNF, estrogen/estrogen receptor, may be involved in the gender different mechanism in stress and depression." (PMID 21785720, 2011). "Similarly, the interaction between the 5-HTTLPR serotonin transporter polymorphism and Val66Met BDNF gene variant was significantly associated to depression originated by stressful factors occurring either in childhood or adult life." (PMID 22654714, 2011). "Despite the small number of subjects, our results indicate that classification based on the DNA methylation profiles of CpG I of the BDNF gene may be a valuable diagnostic biomarker for major depression." (PMID 21912609, 2011). "In addition, polymorphisms of BDNF gene are associated with neuroticism, a personality trait linked to increased susceptibility to depression." (PMID 20219105, 2010). "Moreover, chronic defeat stress, an experimental model for depression, elicits selective downregulation of some BDNF splice variants, in the hippocampus." (PMID 20219105, 2010). "The BDNF Val66Met polymorphism may be implicated in depression and is also hypothesized to influence pain mechanisms." (PMID 21049025, 2010). "Depression and the response to chronic stress are often associated with disorders in food-intake behavior, which is influenced by serotonin and by BDNF." (PMID 15876359, 2005). "Additionally, it would be valuable to examine whether 40 Hz tVAS affects plasma biomarkers associated with depression, such as brain-derived neurotrophic factor, interleukin-6, and cortisol." (PMID 40860215, 2025). "For instance, BDNF Val66Met genevariations affect the integrity of the uncinate fasciculus (UF), with depressedindividuals carrying the Met allele showing lower FA in the UF.Furthermore, the BDNF Val66Met polymorphism moderates the correlationbetween FA in the UF and depression severity." (PMID 40352065, 2025). "The Met allele (BDNF Met) may reduce BDNF levels and increase the risk of depression." (PMID 41301929, 2025). "Several large-scale genetic and transcriptomic studies implicate BDNF as a core susceptibility gene in MDD, with polymorphisms such as Val66Met (rs6265) associated with depression severity and treatment outcomes." (PMID 41373485, 2025). "Brain-derived neurotrophic factors (BDNF), as a growth factor associated with the gut microbiota, can be influenced by the gut microbiota through neuroendocrine pathways to regulate its expression, thereby modulates hippocampal neurogenesis and contributes to the onset and progression of depression." (PMID 41195402, 2025). "The stimulation of the CREB/BDNF pathway in the amygdala subsequent to psychological stress has been associated with the overexpression of synaptic GluA1 through mTOR signaling, thus disrupting the synaptic plasticity of the amygdala and ultimately promoting depression." (PMID 41465304, 2025). "The immediate-early gene c-Fos, associated with the synaptic plasticity mechanism of depression, is activated quickly and briefly in response to a variety of cell stimuli and, in turn, controls the expression of some late response genes, such as BDNF and further regulates various cell reactions." (PMID 40655156, 2025). "Thus, the biological responses of glial cells to BDNF mimetics are crucial, and further investigation into the mechanisms underlying glial contribution to neuronal functions and their roles in the pathophysiology of depression is essential." (PMID 40005159, 2025).
depression (continued). "Furthermore, the neurotrophic hypothesis suggests that compromised levels of BDNF, a key player in neuronal survival and plasticity, are linked to the pathophysiology of depression." (PMID 40224525, 2025). "At the same time, persistent neuroinflammation impairs neurotrophic factor expression (e.g., BDNF) and neurotransmitter systems (e.g., serotonin, dopamine), leading to synaptic dysfunction and neuronal atrophy, all of which are strongly linked to the pathophysiology of depression." (PMID 40941042, 2025). "Given the importance of BDNF in neuronal health, it is hypothesized that the Val66Met variant could influence the development of neuropsychiatric symptoms in MS patients, particularly depression." (PMID 40003622, 2025). "Depression is a common yet potentially debilitating mood disorder with complex neurobiological underpinnings, including deficiencies in monoaminergic and glutamatergic signaling, overactivity of the lateral habenula, and dysregulation of brain-derived neurotrophic factor (BDNF) signaling." (PMID 40453264, 2025). "The BDNF gene may be associated with the putative common pathophysiology of depression and anxiety." (PMID 38255861, 2024). "The gene encoding the brain-derived neurotrophic factor (BDNF) is particularly relevant in this regard as genome-wide association study (GWAS) associated polymorphisms around the BDNF gene locus have been associated with conditions including depression, anxiety and obesity." (PMID 38228888, 2024). "In this study, we aimed to understand whether MGO, administered rectally, can induce depression like-behavior and memory loss in mice and to determine whether impaired BDNF/TrkB signaling, and antioxidant defense system or activation of oxidative stress are involved in the underlying effects of MGO." (PMID 39574138, 2024). "The “neurotrophic hypothesis of depression” posits that disrupted neurotrophic activity is associated with stress-induced depressive behavior and that antidepressant therapies promote the expression of BDNF." (PMID 38916735, 2024). "Many of the presented findings potentially link to biomolecular underpinnings of affective disorders, e.g. decreased BDNF levels or TrkB signaling could underly depression, or neuroinflammation due to immunological hyperactivity could mediate anxiety symptomatology." (PMID 39254764, 2024). "Deviations in BDNF expression are linked to the pathogenesis and therapeutic responses of various mental, behavioral, and neurodevelopmental disorders, such as schizophrenia, eating disorders, depression, substance addiction, as well as other forms of mental and cognitive impairment." (PMID 38988887, 2024). "In recent years, there has been growing evidence to show that the brain-derived neurotrophic factor (BDNF)/TrKB pathway can modulate serotonin (5-hydroxytryptamine; 5-HT) and other neurotransmitters, and this pathway has been implicated in the pathophysiology and treatment of depression and anxiety." (PMID 38907644, 2024). "Furthermore, recent studies have directly confirmed that neuronal reduction can cause anxiety and depression with neuro‐pathological consequences, whereas high expression of BDNF promotes neuronal regeneration and repair, thereby alleviating depressive behavior." (PMID 38376033, 2024). "Additionally, BDNF, implicated in neuroplasticity, has shown promise as a serum biomarker for depression, where decreased levels may predispose individuals to depression." (PMID 38892791, 2024). "However, it is still a matter of debate whether BDNF is a causal factor leading to depression or a correlate of depression." (PMID 39194496, 2024). "Likewise, psychiatric disorders like eating disorders, schizophrenia, and major depression have also been related to disrupted BDNF levels, indicating that BDNF dysfunction may be a common trail underlying different mental health situations." (PMID 39596862, 2024).
depression (continued). "Moreover, seasonality and BDNF Val66Met polymorphism influences the depression outcome in patients." (PMID 38473717, 2024). "Moreover, one extensively supported hypothesis regarding depression is the neurotrophic hypothesis, positing that the pathogenesis of depression is associated with impaired functioning of the BDNF system within the brain." (PMID 38469409, 2024). "Given BDNF's crucial role in the survival of diverse CNS structures, enhanced methylation could impede neuronal repair in stroke-impacted brain regions, heightening depression susceptibility." (PMID 38377025, 2024). "Therefore, early changes in BDNF expression could be characteristic of depression susceptibility as well as a depression state in adolescence." (PMID 38542252, 2024). "Notably, the synergistic interaction among low serum zinc concentrations, GPR39, BDNF, and serotonergic system may be an underlying mechanism of depression." (PMID 37434135, 2023). "While schizophrenia and depression are distinct conditions with different symptoms and diagnostic criteria, it was of interest to investigate whether these differences are also reflected in BDNF gene variant frequencies." (PMID 37626739, 2023). "Furthermore, it has recently been proposed that a supraspinal decrease in BDNF levels is associated with an increase in serum IFNγ, which could therefore be used as an early peripheral marker for depression." (PMID 37530884, 2023). "Furthermore, the results of the included studies regarding the association of BDNF level with sex, quality of life, illness duration, depression, and the use of various medications (e.g., analgesics, antidepressants, etc.)in patients with FM were controversial." (PMID 38127937, 2023). "In conclusion, emerging evidence highlights that several genetic polymorphisms implicated in serotoninergic and dopaminergic neurotransmission and metabolism and neurotrophic factors, especially BDNF, circadian rhythm, and the endocannabinoid system, may affect depression risk in PD." (PMID 37374342, 2023). "Therefore, in a group of mice already submitted to a behavioral test of depression, we examined the expression of some neurotrophic/growth factors associated with the pathogenesis of depressive disorders, such as BDNF, IGF-1, nerve growth factor (NGF), and fibroblast growth factor 2 (FGF-2)." (PMID 37298063, 2023). "Reduced leptin concentration and increased BDNF levels in physically fit adolescents are related to lower levels of depression and have also been positively associated with memory function, which may be related to lower depressive symptoms and cognition, positively influencing AP." (PMID 36264339, 2023). "Furthermore, BDNF can also be found circulating in blood, examined as a potential biomarker for psychiatric disorders, as reduced serum BDNF levels have been associated with various mental disorders (e.g., depression, schizophrenia)." (PMID 37360514, 2023). "Moreover, the effects of eFT508 could be reversed by TrkB/BDNF antagonism, suggesting the critical role of eIF4E in the etiology of neuroinflammation-associated depression via TrkB/BDNF signaling." (PMID 37978167, 2023). "Patients with major depressive disorder have been shown to have a surge in fecal Bacteroidetes, Proteobacteria, and Actinobacteria, as well as a decrease in fecal Faecalibacterium, all of which are associated with low levels of brain-derived neurotrophic factor (BDNF) in the serum." (PMID 36678130, 2023). "Studies on animal models show the tendency of developing BDNF-deficient-related diseases such as depression or anxiety is higher in female animals, and that sex hormones or steroids can modulate the activities of BDNF, which may account for its functional discrepancy in different sexes." (PMID 36983683, 2023).
depression (continued). "For instance, the activation of NF-κB has been linked to neuroprotective and neurodegenerative actions and it might be related to the decreased risk of depression through the upregulation of BDNF, but NF-κB is also related to increased neuroinflammation, a risk factor for depression." (PMID 37334045, 2023). "Hence, the association of WASO with BDNF variants as well as BDNF methylation could be modulated by psychotropic drugs (consisting of benzodiazepines or z‐drugs for 84.7% in our sample), independently of depression." (PMID 36737401, 2023). "In addition, BDNF is a particularly relevant target of MeHg because BDNF polymorphisms increase the susceptibility to neurotoxicity and MeHg-induced BDNF downregulation has been associated with depression." (PMID 36901772, 2023). "While disruption of the BDNF promoter I impairs the response to neuronal depolarization and enhances aggression in mice, disruption of promoter IV has been associated with impaired inhibitory neuronal activity in the prefrontal cortex, leading to depression-like behavior in mice." (PMID 37238659, 2023). "The neurotrophic hypothesis suggests that brain-derived neurotrophic factor (BDNF) and other neurotrophic factors may be involved in the development of depression, and reductions in BDNF have been linked to atrophy of brain regions involved in emotion, such as the hippocampus." (PMID 37089558, 2023). "However, it is inconclusive whether ECT is associated with elevated BDNF levels in studies of patients with depression." (PMID 36457756, 2022). "BDNF has been implicated in a variety of brain disorders such as neurodevelopmental disorders (e.g., autism spectrum disorder), neuropsychiatric disorders (e.g., anxiety, depression, PTSD, and schizophrenia), and various neurodegenerative disorders (e.g., Parkinson’s, Alzheimer’s, etc.)." (PMID 35732627, 2022). "Thus, PVH BDNF signaling to NTS TrkB expressing cells may underlie stress-responsive cardiovascular responses which may become altered in depression due to adaptations after chronic stress." (PMID 36466807, 2022). "Interestingly, BDNF is potentially associated with obesity, depression and coronary syndromes." (PMID 35911513, 2022). "Finally, further research would be required to assess whether the effect of physical activity on depression risk in longitudinal studies is moderated by the BDNF Val66Met genotype." (PMID 35206257, 2022). "Moreover, BDNF is associated with a number of psychiatric syndromes, including depression." (PMID 35370811, 2022). "Decreased peripheral expression of BDNF certainly presents a risk of depression, but in our sub‐group analysis, alcohol consumption and history of depression, unlike age and gender, may have influenced the outcome of our results, a novel finding that has not been previously reported." (PMID 35510613, 2022). "Some clinical researches also evidenced this association between the BDNF Met carrier and lower BDNF levels in the patients with major depressive disorder, schizophrenia, and bipolar disorder respectively, suggesting the Met allele may play a key role in regulating BDNF protein expression." (PMID 35815047, 2022). "As described in detail in this review, BDNF is associated with sleep on multiple levels, from modulating the sleep structure itself to participation in the pathophysiology of mental disorders featuring disrupted sleep, such as depression or anxiety, which accompany immune-related conditions." (PMID 36294343, 2022). "MYR administration significantly reversed the SPS-induced reduction of BDNF mRNA expression, which suggests that its beneficial effects on depression- and anxiety-like behaviors were mediated by an increase in BDNF expression that may be associated with enhanced neuronal function." (PMID 35722162, 2022). "BDNF gene polymorphisms may be risk factors for the development of depression and interact with the genetic environment to play a role in the development of depression." (PMID 36297314, 2022).
depression (continued). "Therefore, scientists assumed that the pathogenesis of depression might be associated with altered cytokines, chemokines, BDNF, GDNF, neurotrophins, and growth factors in the human body." (PMID 36409748, 2022). "Considering that the studied cohort predominantly comprises overweight individuals, our findings are two fold: depression is directly related to a higher number of platelets, as in normal weight people; and the positive association between platelet number and depression score was mitigated by BDNF." (PMID 35911513, 2022). "Similarly, in a study carried out in Slc6a41Hubr rats with knockout of the 5-HT transporter (SERT−/−), a decrease in the BDNF levels was detected, which was associated with a reduction in sucrose intake (anhedonia) and severe depression-like behavior in the forced swim test (FST)." (PMID 36142808, 2022). "This hypothesis proposes that depression results from decreased BDNF-mediated support leading to neuronal atrophy, decreased neurogenesis and loss of glia in the HC, and that antidepressant treatment blocks or reverses this BDNF deficit." (PMID 36499323, 2022). "BDNF gene may be implicated in the putative common pathophysiology of depression and anxiety." (PMID 35815047, 2022). "Imbalances in the levels of monoamine neurotransmitters or neurotrophic factors are the main hypotheses for the pathogenesis of depression, based primarily on deficiencies in biogenic amine systems or brain-derived neurotrophic factor (BDNF) signaling, respectively." (PMID 36339629, 2022). "Therefore, we affirmed that the expression of the P2X7 receptor was negatively associated with BDNF concentration, and gallic acid could alleviate depression via P2X7 receptor downregulation and BDNF elevation." (PMID 35682841, 2022). "For example, single nucleotide polymorphism (SNP) in the BDNF gene, whereby valine residue is replaced with methionine residue in codon 66 (Val66Met), would ultimately impair neuronal activity-mediated BDNF secretion and cause the person to be more vulnerable to depression." (PMID 36499240, 2022). "However, the molecular mechanisms underlying the crosstalk between Nrf2 and BDNF in depression remain unclear." (PMID 33627628, 2021). "However, the precise molecular mechanisms underlying Nrf2 and BDNF crosstalk in depression are currently unknown." (PMID 33627628, 2021). "However, previous studies have reported that physical activity including aerobic exercise may reverse the risk of aging-related depression by promoting BDNF production and increasing hippocampal volume." (PMID 35002797, 2021). "In particular, high methylation of CpG sites in exon I and low serum levels of BDNF were associated with MDD and depression in patients characterized by bipolar II disorders." (PMID 33643008, 2021). "A large study investigated the role of BDNF methylation in MDD patients and its association with depression therapy." (PMID 33804455, 2021). "Furthermore, it has been observed that subjects carrying the Val66Met (rs6265) single nucleotide polymorphism (SNP), which has been shown to affect intracellular trafficking and secretion of BDNF, are at higher risk for developing major depressive disorder (MDD) compared to Val/Val subjects." (PMID 33995104, 2021). "Another study, using a chronic unpredictable mild stress model to induce depression-like behaviour in animals showed that exposure to musk stimulated neurogenesis and reduced the neuronal apoptosis in the hippocampus, which is associated with the upregulation of hippocampal BDNF levels." (PMID 34063646, 2021). "Thus, the up-regulation of BDNF levels may be a new mechanism underlying the therapeutic effects of BoNT/A in the management of depression." (PMID 33967844, 2021). "Szuhany and Otto's studies of outpatients with MDD and persistent depression demonstrated that both acute and regular exercise caused an increase in BDNF." (PMID 34803752, 2021).